G6PD (glucose-6-phosphate dehydrogenase)
Diseases named in the same sentence as G6PD in open-access papers (continued):
Sharing a sentence is not in itself a finding about the gene and the disease.
G6PD deficiency (continued). "Primaquine therapy can result in severe acute haemolysis in patients with glucose-6-phosphate dehydrogenase (G6PD) deficiency." (PMID 22727113, 2012). "G6PD deficiency is caused by one or more mutations in the G6PD gene on chromosome X, which lead to functional variants of the protein resulting in different biochemical and clinical phenotypes." (PMID 23006493, 2012). "The geographical distribution of G6PD deficiency offers strong evidence for its selection by malaria; increased oxidative stress in G6PD-deficient red blood cells is assumed to reduce parasite replication and thereby confer protection." (PMID 23144702, 2012). "Tafenoquine, like other 8-aminoquinolines such as primaquine, induced haemolytic anaemia in individuals with glucose-6-phosphate dehydrogenase (G6PD) deficiency." (PMID 21801400, 2011). "During monotherapy treatment, the compound exhibits slow parasite and fever clearance times, and toxicity in glucose-6-phosphate dehydrogenase (G6PD) deficiency is a concern." (PMID 21801400, 2011). "The clinical consequences of drug-induced G6PD deficiency-related hemolysis depend on several factors including the kinetic properties of the G6PD variant." (PMID 21977034, 2011). "We assessed a kit under research and development called CareStartTM G6PD deficiency screening test (Access Bio, New Jersey, USA) by comparing its performance to quantitative G6PD enzyme activity using a standardized spectrophotometric method (‘gold standard’)." (PMID 22164279, 2011). "G6PD deficiency is common in African patients with malaria and until a reliable and simple G6PD test is available, the use of 8-aminoquinolines will remain problematic." (PMID 21849081, 2011). "Results of the CareStartTM G6PD deficiency screening test® and the quantitative G6PD assay from 903 individuals, Pailin province, Cambodia, 2010." (PMID 22164279, 2011). "Primaquine is contraindicated in patients with severe glucose-6-phosphate dehydrogenase deficiency, therefore, in regions where prevalence of G6PD deficiency is relatively high, G6PD testing is required before administration of primaquine." (PMID 21184691, 2010). "Primaquine is contraindicated in case of glucose-6-phosphate dehydrogenase (G6PD) deficiency, due to the risk of hemolysis." (PMID 20618990, 2010). "Currently, in most places where P. vivax malaria is common, primaquine is not given routinely because primaquine can trigger red blood cell death (hemolytic anemia) in G6PD-deficient people and tests for G6PD deficiency are rarely available." (PMID 20520804, 2010). "In areas where P. vivax malaria is common, Mediterranean and Asian variants of G6PD deficiency are more widespread than A− G6PD, so the question is, do these variants protect against P. vivax malaria?" (PMID 20520804, 2010). "Before treatment, the median parasitaemia and other baseline characteristics (mean haemoglobin, sex and age groups) between G6PD deficiency (hemizygous, heterozygous, and homozygous) and G6PD-normal participants were comparable (p > 0.05)." (PMID 21092137, 2010). "The current study revealed a high prevalence of G6PD deficiency among Iraqi Kurdish population of Northern Iraq with most cases being due to the G6PD Mediterranean and Chatham variants." (PMID 20602793, 2010). "DNA analysis was performed on 115 G6PD deficient subjects, 50 from the premarital screening group and 65 unrelated Kurdish male patients with documented acute hemolytic episodes due to G6PD deficiency." (PMID 20602793, 2010). "Of the 112 anaemia cases in the non-malaria infected group, 42% had some type of haemoglobinopathy (HbAS=10%, G6PD deficiency=6% and mutant α-globulin gene=25%) compared to 25% (HbAS=6%, G6PD-=4% and α*=16%) of non anaemic children." (PMID 21144084, 2010). "Primaquine causes abdominal discomfort, particularly if taken on an empty stomach, and potentially serious haemolytic anaemia in patients with glucose-6-phosphate dehydrogenase (G6PD) deficiency." (PMID 20832366, 2010).
G6PD deficiency (continued). "Exceptions were for patients with pre-existing renal insufficiency/failure or glucose 6-phosphate dehydrogenase (G6PD) deficiency, both known to predispose to vitamin C toxicity." (PMID 20628650, 2010). "Overall, the main risk factors associated with the composite endpoint were G6PD deficiency versus G6PD normal (OR 16.3, 95%CI 8.6, 31.2) and CDA treatment versus AL (OR 5.1, 95%CI 2.1, 12.4)." (PMID 19690618, 2009). "We compared the association between uncomplicated malaria incidence and G6PD deficiency in a cohort of 601 Ugandan children using two different diagnostic methods, enzyme activity and G6PD genotype (G202A, the predominant East African allele)." (PMID 19789650, 2009). "Of 62 people with enzymatically determined G6PD deficiency, we were unable to identify a deficiency-causing variant in ∼25% (16/62) after assessing the three common G6PD A- variants found in African populations." (PMID 19789650, 2009). "G6PD deficiency is a major risk factor for haemoglobinuria in Vietnamese Kinh and within the G6PD deficient population G6PD Viangchan was significantly associated with haemoglobinuria." (PMID 19589177, 2009). "This study underscores the impact that the method of identifying G6PD deficient individuals has upon association studies of G6PD deficiency and uncomplicated malaria." (PMID 19789650, 2009). "G6PD deficiency, as determined by G6PD enzyme activity, conferred a 52% (relative risk [RR] 0.48, 95% CI 0.31–0.75) reduced risk of uncomplicated malaria in females." (PMID 19789650, 2009). "G6PD deficiency is a common chromosome x-linked red blood cell enzymopathy with several polymorphisms arisen from mutations in the G6PD gene." (PMID 19460160, 2009). "Microscopically detected parasite carriage has been associated with several red blood cell polymorphisms, such as α+-thalassaemia, sickle cell trait and glucose 6 phosphate dehydrogenase (G6PD) deficiency." (PMID 19460160, 2009). "The frequency of G6PD deficiency was 9.7% (45/464; G6PD A heterozygotes) and 3.7% (17/464; G6PD A-homozygous/hemizygous)." (PMID 19460160, 2009). "This study underscores the impact that the method of identifying G6PD deficient individuals has upon studies of G6PD deficiency and malaria." (PMID 19789650, 2009). "This is what makes drug-induced G6PD deficiency-related hemolytic anemia in G6PD A− subjects a self-limiting problem in most cases." (PMID 19370159, 2009). "We performed an extensive analysis of 1311 C/T polymorphism of G6PD gene within normal Pakistani population and in subjects with G6PD deficiency." (PMID 19640310, 2009). "Glucose 6-phosphate dehydrogenase (G6PD) deficiency is one of the most frequent red cell enzymopathies affecting some 400 million people globally." (PMID 19640310, 2009). "The frequency of G6PD deficiency was similar to other studies performed in Brazil and the finding of a predominant G6PD A− variant will help the clinical management of patients with drug-induced haemolysis." (PMID 19370159, 2009). "The degree of drug-induced G6PD deficiency related haemolysis depends on a number of factors including the G6PD variant, the drug and dosage, and poorly characterised disease factors." (PMID 19112496, 2008). "Due to the potential protective effect of G6PD-deficiency from malaria, G6PD deficiency is probably selected in malaria endemic regions, in a similar manner as for other haemoglobinopathies." (PMID 17925871, 2007). "Similarly, absolute reticulocyte count was higher in the group with G6PD deficiency compared to the group with normal G6PD activity (94.1 ± 27.6 vs. 70.4 ± 20.6, P < 0.001)." (PMID 41575919, 2026). "G6PD deficiency is an X-linked recessive disorder that affects the activity of the G6PD enzyme." (PMID 39823117, 2025). "Notably, four out of five individuals with confirmed glucose-6-phosphate dehydrogenase (G6PD) deficiency were diagnosed during malaria treatment." (PMID 40639370, 2025).
G6PD deficiency (continued). "SCR correlated significantly with higher vaso-occlusive crises (VOC) frequency (ρ = 0.379, p < 0.001), lower fetal hemoglobin (HbF) (ρ = -0.363, p = 0.001), older age (r = 0.295, p = 0.006), and glucose-6-phosphate dehydrogenase (G6PD) deficiency (ρ = 0.428, p < 0.001)." (PMID 40848190, 2025). "Therefore, comprehensive education is essential at discharge for children at risk of or diagnosed with G6PD deficiency, emphasizing the avoidance of herbal remedies for jaundice treatment to mitigate the risk of G6PD-induced hemolysis." (PMID 40168352, 2025). "Logistic regression analysis identified preterm birth (<37 weeks), ABO hemolysis, Glucose-6-Phosphate Dehydrogenase (G6PD) deficiency, and Total Serum Bilirubin (TSB) level at discharge as significant predictive factors for readmission due to hyperbilirubinemia in newborns." (PMID 40168352, 2025). "Detection of mutations in G6PD confirmed the diagnosis of G6PD deficiency." (PMID 40527851, 2025). "This overlap poses a unique therapeutic dilemma because methylene blue, the standard treatment for methemoglobinemia, requires nicotinamide adenine dinucleotide phosphate generated via the G6PD pathway and is, therefore, contraindicated in people with G6PD deficiency." (PMID 41216053, 2025). "Methylene blue is contraindicated in cases of glucose-6-phosphate dehydrogenase (G6PD) deficiency." (PMID 41439050, 2025). "There were three cases of malignancy (acute myeloid leukemia, myelodysplastic syndrome and neuroblastoma, respectively) and three cases of benign hematologic diseases (chronic neutropenia, glucose-6-phosphate dehydrogenase (G6PD) deficiency and hereditary spherocytosis, respectively)." (PMID 39846608, 2025). "Notably, <0.5% of G6PD p.Val68Met hemizygotes and homozygotes across all cohorts had a clinical G6PD deficiency diagnosis." (PMID 41362833, 2025). "Importantly, the use of MB is contraindicated in pregnant patients, or with renal insufficiency, glucose-6-phosphate dehydrogenase (G6PD) deficiency, Heinz body anemia, and selective serotonin(-norepinephrine) reuptake inhibitors." (PMID 41376874, 2025). "The geographical distribution of G6PD deficiency strongly correlates with the historical prevalence of malaria, supporting the hypothesis that heterozygous G6PD mutations confer a selective advantage against Plasmodium falciparum infections." (PMID 40486677, 2025). "An example of this situation is glucose-6-phosphate dehydrogenase (G6PD) deficiency." (PMID 41362833, 2025). "Therefore, we present a rare case of low oxygen saturation in a patient with glucose-6-phosphate dehydrogenase (G6PD) deficiency and variant hemoglobin (elevated HbA2) on risperidone therapy, who exhibited no respiratory compromise." (PMID 41306179, 2025). "There is still a need to be cautious in patients with renal failure, history of nephrolithiasis, or glucose-6-phosphate dehydrogenase (G6PD) deficiency, in which excess ascorbate may theoretically trigger oxalate nephropathy or hemolysis." (PMID 41465314, 2025). "Tafenoquine may cause severe haemolysis in individuals with < 70% of normal G6PD activity, and treatment is withheld in males and females with severe G6PD deficiency and heterozygous females if they have G6PD activity below this threshold." (PMID 41345660, 2025). "Patients known to have G6PD deficiency should avoid fava beans (especially fresh raw fava beans) and drugs that induce hemolysis, while, the G6PD gene must be detected in methemoglobinemia patient before the treatment with methylene blue, especially the co-occurrence happened." (PMID 40527851, 2025). "However, the incidence rate of G6PD deficiency and the frequency of the most common G6PD gene variants vary widely." (PMID 39076173, 2024). "A review from Italy also discussed the advantages and disadvantages of G6PD, suggesting that G6PD deficiency may provide benefits with respect to malaria, cancer development, and coronary disease and may also have positive effects on longevity." (PMID 39726786, 2024).
G6PD deficiency (continued). "If primaquine or tafenoquine are indicated, quantitative glucose-6-phosphate dehydrogenase (G6PD) testing should be conducted before administration because of risk of hemolytic anemia and need for a modified regimen or alternative medication if G6PD deficiency is detected." (PMID 39446670, 2024). "Glucose-6-phosphate dehydrogenase (G6PD) deficiency is an X-linked gene disorder in which treatment with oxidizing drugs, such as sulfonamides, dapsone, primaquine, can directly destroy hemoglobin present in red blood cells (RBCs), thereby inducing methemoglobin and hemolysis." (PMID 39318598, 2024). "Patients with severe G6PD deficiency had significantly decreased G6PD activity (1.11 ± 0.90) compared to normal controls (15.96 ± 3.03; P < 0.001), while the G6PD activity of those with moderate G6PD deficiency (8.63 ± 0.67) did not significantly differ compared to normal controls." (PMID 38992151, 2024). "Since prolonged jaundice may be the first sign of G6PD deficiency, the enzyme level should be checked in newborns diagnosed with this condition, and G6PD should be more strongly suspected over PK in prolonged neonatal jaundice due to breast milk jaundice." (PMID 39336532, 2024). "A nested cohort study found that haemolysis after primaquine was greater in 33 female patients heterozygous for G6PD deficiency than in 198 patients with wild-type G6PD, with increased haemolysis in heterozygous patients after receiving 1 mg/kg per day of primaquine compared with 0·5 mg/kg per day." (PMID 37748497, 2024). "However, all 8-aminoquinoline drugs cause oxidant haemolysis in people with glucose-6-phosphate dehydrogenase (G6PD) deficiency." (PMID 39236082, 2024). "Notably, within the Thai population, genetic disorders that manifest with a comparatively higher prevalence than in other populations encompass thalassemia, hemoglobinopathies, and glucose-6-phosphate dehydrogenase (G6PD) deficiency." (PMID 38167091, 2024). "However, both drugs can lead to acute haemolysis in patients with glucose-6-phosphate dehydrogenase (G6PD) deficiency." (PMID 38254128, 2024). "This impaired inflammasome responsiveness in G6PD deficiency may also in part explain the decreased body temperatures seen in G6PD-deficient patients with malaria." (PMID 38938571, 2024). "The present study aimed to investigate the clinical and laboratory characteristics of patients with hepatitis A virus (HAV) infection, with a specific focus on the presence of glucose-6-phosphate dehydrogenase (G6PD) deficiency and the occurrence of encephalopathy." (PMID 39011425, 2024). "However, the currently available drugs to eliminate hypnozoites (8-aminoquinolines), can cause haemolysis in patients with glucose-6-phosphate dehydrogenase (G6PD) deficiency." (PMID 38725027, 2024). "Moreover, there was a notable disparity in the incidence rates of each inherited anemia type between genders, with males exhibiting the highest incidence rates in G6PD deficiency and females in G6PD trait." (PMID 38079097, 2024). "However, to reduce the risk of hemolytic anemia, especially in patients with G6PD deficiency, a G6PD level should be checked before starting these treatments." (PMID 39449945, 2024). "Comparison of ROC curves of G6PD activity in predicting G6PD deficiency between seasons." (PMID 38496015, 2024). "Finally, the mutation G6PD Madrid was identified in two Spanish males with G6PD deficiency and hemolytic anemia." (PMID 39684266, 2024). "NMP participant ranked factors such as malaria program phase, vivax case load, G6PD prevalence, G6PD deficiency heterogeneity, liver stage treatment, antirelapse efficacy, patient adherence, human resources, and risk aversion as having a high importance for policy making." (PMID 38776349, 2024).
G6PD deficiency (continued). "This male patient, 3bINP-085, also presented co-occurrence with X-linked hemolytic anemia due to G6PD deficiency (OMIM #300908), which was attributed to the most prevalent worldwide G6PD haplotype, c.[202G>A;376A>G], or p.[Val68Met;Asn126Asp], conditioning G6PD deficiency." (PMID 39519275, 2024). "In addition to being used for the diagnosis of G6PD deficiency, genotyping of G6PD is also mainly used for epidemiological investigations and further exploration research on genotype-phenotype correlations." (PMID 39076173, 2024). "G6PD deficiency is rare in Japan, with approximately 21 G6PD variants being characterized." (PMID 39726786, 2024). "However, the dose must be adjusted in individuals with glucose-6-phosphate-dehydrogenase (G6PD) deficiency." (PMID 38725027, 2024). "A repeat G6PD screen confirmed the diagnosis of G6PD deficiency." (PMID 39170996, 2024). "Future studies are planned to correlate whether G6PD deficiency in this population is associated with abnormal liver function tests and to establish the true G6PD prevalence in the African American community in the United States." (PMID 38132231, 2023). "Identified challenges include optimal training of health facility staff on point-of-care diagnostics, quality control of novel G6PD diagnostics, and culturally appropriate information and communication with affected communities around G6PD deficiency and implications for treatment." (PMID 37242320, 2023). "G6PD genotypes distribution in 268 cases of G6PD deficiency." (PMID 38264207, 2023). "Finally, the unclassified G6PD Mexico DF was detected in male volunteer blood donors in a genetic and molecular study of G6PD deficiency in Northern Mexico." (PMID 37628871, 2023). "In this paper, performance data for the STANDARD G6PD POC test for G6PD deficiency was consolidated from multiple studies conducted on both capillary and venous specimens across seven countries, representing diverse settings and use cases for G6PD testing." (PMID 37824592, 2023). "In conclusion, the findings of the present study suggest that X-chromosome skewing, associated with normal and deficient G6PD, may partly modulate the pro-inflammatory effect of G6PD deficiency." (PMID 36829893, 2023). "The CareStartTM G6PD RDT performed well in discriminating G6PD deficiency with 88% PPV and 99% NPV." (PMID 37127600, 2023). "According to our prevalence study, most of the G6PD-deficient Senoi Orang Asli population had G6PD deficiency with enzyme activity less than 30% of AMM (9.8%, 36/369), while only 5.4% (20/369) of the subjects had intermediate deficiency with enzyme activity between 30% to 80% of AMM." (PMID 38085718, 2023). "However, while data on the general population’s prevalence of G6PD deficiency is available, limited information exists regarding the range of G6PD variants in specific regions and ethnic groups." (PMID 38264207, 2023). "In recent years, several G6PD PoC tests have been developed, including lateral flow qualitative tests to identify G6PD deficiency at around 30% of normal G6PD activity as well as quantitative handheld devices (biosensors) that can identify individuals with intermediate activity." (PMID 37242320, 2023). "Parental knowledge of G6PD risk factors, with an adjusted odds ratio (adjOR) of 2.5, suggests that those aware are 2.5 times more likely to have a child with G6PD deficiency, highlighting an increased likelihood of G6PD deficiency in their children." (PMID 38229803, 2023). "Understanding G6PD treatment, fluid intake, and blood transfusion plays a crucial role, and awareness in these areas is linked to a higher likelihood of having a child with G6PD deficiency." (PMID 38229803, 2023). "However, there was a lower prevalence of G6PD deficiency among the Indian ethnicity, where some individuals were found to carry different variants including G6PD Namoru (c." (PMID 38085718, 2023).